SNORD73A (small nucleolar RNA, C/D box 73A)
Synonyms: U73a; RNU73A; RNU73; U73
Gene: Small nucleolar RNA gene on chromosome 4 (151,103,827 to 151,103,891, forward strand). Ensembl gene ENSG00000208797.
Gene Ontology:
Biological process: RNA processing
Cellular component: nucleolus
Homologues: Orthologues: chimpanzee SNORD73 (100% identical), macaque SNORD73 (95% identical), guinea pig SNORD73 (91% identical), pig SNORD73 (91% identical), rabbit SNORD73 (91% identical), rat Snord73a (89% identical), mouse Snord73a (88% identical), rabbit SNORD73 (85% identical), dog SNORD73A (83% identical). Paralogues in human: SNORD73B (75% identical).